LRIG2 (leucine rich repeats and immunoglobulin like domains 2)
Diseases named in the same sentence as LRIG2 in open-access papers (continued):
Sharing a sentence is not in itself a finding about the gene and the disease.
tumor (continued). "The protein expression of LRIG2 was only observed in the cytoplasm of the tumor tissue, which conformed to the mRNA expression results." (PMID 25013483, 2014). "For example, the expression of another possible tumor suppressor, LRIG2, in early-stage erythrocytes and monocytes is accurately predicted (p-value <0.01) using K562 CRMs, but its expression in late-stage erythrocytes and monocytes is not predicted accurately." (PMID 22721266, 2012). "Silencing LRIG2 also suppressed the growth of subcutaneous transplanted tumor in nude mice." (PMID 36183058, 2022). "We found that silencing LRIG2 significantly decreased the rate of tumor growth and tumor size." (PMID 36183058, 2022). "It would be important to determine how LRIG2 functioned in OS cells and other tumor cells." (PMID 36183058, 2022). "Moreover, RT-qPCR and western bolt assays showed that the mRNA and protein expression of LRIG2 were dramatically attenuated in tumor tissues relative to that in normal tissues." (PMID 32863771, 2020). "Our data suggest that LRIG2 is involved in tumor progression and accelerates tumorigenesis." (PMID 31580518, 2019). "Thus, LRIG2 functions as either a tumor suppressor or an oncogene likely depending on the cellular context, similar to its well-characterized homolog, LRIG15,6." (PMID 29358688, 2018). "The tumor promoting effects of LRIG2 on receptor tyrosine kinases (RTKs) might be prominent in tumor cells and subtle in non-tumor cells." (PMID 25353163, 2014). "LRIG2 localization in the cytoplasm may augment its action as a tumor promoter, whereas the perinuclear localization of LRIG2 may act as a tumor suppressor." (PMID 25013483, 2014). "The present study evaluated the mRNA expression of LRIG2 in tumor specimens obtained from 39 NSCLC patients by SYBR Green quantitative polymerase chain reaction and the protein expression of LRIG2 in formalin-fixed paraffin sections obtained from 116 NSCLC patients by immunohistochemistry." (PMID 25013483, 2014). "Additionally, silencing LRIG2 significantly decreased the rate of tumor growth and tumor size." (PMID 36183058, 2022). "However, other tumor-promoting effects of Lrig2 cannot be excluded, at present." (PMID 24023893, 2013). "While LRIG2 has been described as a tumor promoter, LRIG1 and LRIG3 have been identified as tumor suppressors in previous literature." (PMID 41201961, 2025). "At the molecular level, the encoded transmembrane protein LRIG1 acts as a negative regulator of growth factor signaling; the LRIG2 protein works as a tumor promotor; and the LRIG3 protein functions as a tumor suppressor." (PMID 33802837, 2021). "To determine whether LRIG2 affects skin tumorigenesis, we performed a two‐stage chemical skin carcinogenesis model with onetime application of DMBA on the back skin of LRIG2‐TG mice and control littermates causing tumor initiation followed by TPA treatment twice a week." (PMID 31580518, 2019). "In conclusion, epidermal LRIG2 excess is associated with activated EGFR/ERBB4‐MAPK signaling and accelerated tumor progression in experimentally induced NMSC, suggesting LRIG2 as a potential oncoprotein in skin." (PMID 31580518, 2019). "Whereas tumor‐suppressive functions of LRIG1 and LRIG3 have been reported in malignant glioma, LRIG2 seems to act more as an oncoprotein." (PMID 31580518, 2019). "We used immunohistochemistry to investigate LRIG1, LRIG2, and LRIG3 expression in tumour samples from a consecutive cohort of 70 PVC patients." (PMID 28841699, 2017). "In the present study, the mRNA expression of LRIG2 was decreased in NSCLC cancer tissues and found to correlate with histological subtypes and tumor differentiation status." (PMID 25013483, 2014). "Although these effects of LRIG2 have no obvious impact on skin homeostasis, LRIG2‐TG mice showed an increased tumor progression compared with control littermates during two‐stage chemical skin carcinogenesis." (PMID 31580518, 2019).
tumor (continued). "We found the expression of THBS1 and MMP9 to be increased in LRIG2‐TG mice 48 h after TPA application, assuming that THBS1 expression could be involved in LRIG2‐mediated tumor initiation and progression." (PMID 31580518, 2019). "Even though LRIG2 overexpression has no obvious major impact on skin development and homeostasis, LRIG2 may promote tumor growth and induce a more severe carcinogenic phenotype, possibly by inactivating the tumor suppressor PTEN." (PMID 31580518, 2019). "To investigate whether the tumor promoting activity of LRIG2 is ERBB receptor‐dependent, we analyzed the expression of the latter and respective downstream targets in transgenic and control skin during two‐stage skin carcinogenesis." (PMID 31580518, 2019). "A majority of the 70 tumours showed LRIG1 and LRIG2 expression in >50% of cells and demonstrated no or low LRIG3 expression." (PMID 28841699, 2017).
cancer (11 papers, 2012 to 2024). A tumor composed of atypical neoplastic, often pleomorphic cells that invade other tissues. "Genes for which we know little about, like LRIG2, but associated with poor prognosis of different cancer types, have been detected by our method to correlate with the expression of three TFs (FOSTAF1 and YY1) across blood cell groups." (PMID 22721266, 2012). "Our study revealed increased LRIG2 expression in cancer cells in vitro, indicating a tumorigenic function of LRIG2." (PMID 31580518, 2019). "It was found that the expression of LRIG2 was decreased in the cancer tissues, indicating a potential role of the LRIG2 protein in the pathogenesis of NSCLC." (PMID 25013483, 2014). "The mean mRNA expression level of LRIG2 in the 39 NSCLC cancer and adjacent cancerous tissues was 0.2288±0.0230 and 0.6185±0.0321, respectively." (PMID 25013483, 2014). "The results showed that the mRNA expression of LRIG2 was decreased in the cancer and adjacent cancerous tissues." (PMID 25013483, 2014). "Interestingly, LRIG2 expression is mostly cytoplasmic in normal, basal epidermis, but nuclear in more differentiated epidermal layers and in cancer cells." (PMID 31580518, 2019). "LRIG2 expression has been investigated in several types of cancer." (PMID 25013483, 2014). "Although LRIG2 has been proven to be of prognostic value in several types of human cancers, the expression status in NSCLC remains unknown." (PMID 25013483, 2014). "Moreover, the absence of any obvious morphogenetic or gross cochlear patterning defects argues against the idea that Lrig1 and Lrig2 act redundantly to control any of the major signaling pathways, consistent with their distinct effects in vitro and in cancer." (PMID 24086156, 2013). "Furthermore, we found that LRIG2 unexpectedly phosphor-activates phosphoinositide 3-kinase (PI3K)/AKT and epidermal growth factor receptor (EGFR), which are conventionally accepted as survival signaling cues in diverse types of cancer." (PMID 29358688, 2018). "Likewise, the current data cannot discriminate between cancer cell autonomous and non-autonomous effects of Lrig2." (PMID 24023893, 2013).
LRIG2 also shares sentences with these, for which no sentence is quoted: cervical adenocarcinoma (2 papers); astrocytic tumor (1); autosomal recessive spastic paraplegia 47 (1); brain tumour (1); chronic kidney failure (1); congenital lower urinary tract obstruction (1); diabetes type 1 (1); frontometaphyseal dysplasia (1); genetic disease (1); influenza infection (1); Lynch syndrome (1); meningioma (1); multiple myeloma (1); oligodendroglial tumor (1); peripheral neuropathy (1); pituitary tumor (1); prune belly syndrome (1); rheumatoid arthritis (1); small cell lung carcinoma (1); systemic lupus erythematosus (1); vesicoureteral reflux (1).